IFNG (interferon gamma)
Diseases named in the same sentence as IFNG in open-access papers (continued):
Sharing a sentence is not in itself a finding about the gene and the disease.
vitiligo (continued). "Posteriorly, an upregulation in interferon-gamma (IFN-γ) gene expression has been identified in the serum from vitiligo patients." (PMID 35360245, 2022). "More precisely, this study further revealed that in the pathogenesis of vitiligo, IFNγ-responsive dermal fibroblasts are not only uniquely required but also sufficient to induce local aggregation of CD8+ T cells." (PMID 35950754, 2022). "IFNγ-chemokine axis has been identified as a potential pathway in the initiation and progression of vitiligo." (PMID 36359263, 2022). "In vivo studies using vitiligo mouse models also support the critical role of the IFNγ/CXCR3/CXCL10 signaling." (PMID 36359263, 2022). "The skin and blood of vitiligo patients, as well as a mouse model, exhibit elevated levels of interferon-gamma and interferon-gamma-induced chemokines (CXCL9 and CXCL10)." (PMID 36475210, 2022). "Using mouse models of vitiligo, this study further confirmed that CD8+ T cells preferentially aggregate toward a region with fibroblasts capable of stronger IFNγ responses, hence generating a patterned loss of melanocytes." (PMID 35950754, 2022). "Candidate gene studies highlight the role of autoimmunity in vitiligo, as polymorphisms in IL1B, IL4, PSMB8, NLRP1, NPY, FOXP3, and IFNG genes were found to be associated with vitiligo." (PMID 36164321, 2022). "These discoveries provided the rationale to test JAK inhibitors, which block IFNγ signaling, as treatments for vitiligo and eventually led to a successful Phase 2 clinical trial to test topical ruxolitinib as a novel treatment for the disease." (PMID 33737930, 2021). "For example, in the pathogenesis of vitiligo, IFNγ-producing CD8 TRM has been shown to play a major role." (PMID 34884736, 2021). "Transcriptome analysis on the skin and blood of patients with vitiligo revealed IFNγ-induced chemokines CXCL10 and CXCL9 were increased." (PMID 34371735, 2021). "Autoreactive TRM cells secreting IFNγ have been described in lesional vitiligo skin and are responsible for disease relapse." (PMID 34371735, 2021). "Attracted by proinflammatory cytokines, autoreactive CD8+ T cells that destroy the pigment-producing cells of melanocytes through the mediation of interferon-gamma (IFN-γ) signaling are believed to promote the apoptosis of melanocytes in vitiligo." (PMID 34970551, 2021). "It is well established that CXCL9 and CXCL10 are induced by IFNγ and function to promote effector T cell infiltration into tumors as well as sites of active depigmentation in the setting of vitiligo." (PMID 34362825, 2021). "Here we show that NK and ILCs from vitiligo patients produce higher amount of IFNγ under oxidative stress but also under the stimulation of the two main DAMPs implicated in vitiligo pathophysiology, namely HSP70 and HMGB1 compared to healthy subjects." (PMID 31097717, 2019). "Our immunofluorescence results have shown that indeed, cytotoxic NK cells (defined as CD56 + Granzyme B+) containing IFNγ (CD56 + IFNγ+) were present in NL human vitiligo skin." (PMID 31097717, 2019). "Their significant increase in the blood and in the NL vitiligo skin argues for their key role in the initial production of IFNγ." (PMID 31097717, 2019). "We sorted NK and total ILCs from PBMC of healthy (C) and vitiligo (V) patients and examined their IFNγ responses 24, 48 and 72 h post stimulation with H2O2 (to induce oxidative stress in cells)." (PMID 31097717, 2019). "Transcriptome analysis on the skin and blood of patients with vitiligo revealed IFNγ-induced chemokines CXCL10 and CXCL9 were increased, which is consistent with the observed abundance of autoreactive T cells expressing the cognate CXCR3 receptor." (PMID 31649667, 2019). "Stimulation of healthy or vitiligo melanocytes with IFNγ induced a significant increase in mRNA expression of CXCL4, CXCL9, CXCL10 and CXCL11." (PMID 31097717, 2019).
vitiligo (continued). "Melanocytes of vitiligo patients have strong basal expression of chemokine-receptor-3 (CXCR3) isoform B which is directly regulated by IFNγ." (PMID 31097717, 2019). "Both alopecia areata and vitiligo are characterized by IFNγ producing autoreactive cytotoxic T lymphocytes that attack hair follicles and melanocytes, respectively." (PMID 31447854, 2019). "The transcripts of IFNG and Th17 specific cytokines remained undetectable in control as well as in vitiligo biopsy samples." (PMID 30515176, 2018). "PSMB8 polymorphism in addition to previously reported susceptibility loci such TNFA, TNFB, IL1B, IFNG, NALP1, IL4 etc. demonstrate immunogenetic predisposition in vitiligo patients from Gujarat." (PMID 28700671, 2017). "Peripheral blood of patients with vitiligo is also characterized by high frequencies of melanocyte-reactive cytotoxic T cells, able to release type B granzyme, perforin, and IFNγ, while perilesional T-cell infiltration can be found in vitiligo epidermis." (PMID 25838868, 2015). "Ruxolitinib's mode of action may entail an interference with interferon-gamma signaling and Janus kinases, as evidenced by the quick improvements seen in individuals with vitiligo and alopecia areata who received treatment for the conditions." (PMID 36475210, 2022). "According to these data, this study proposed that the regional distribution of highly IFNγ-responsible fibroblasts may explain the pattern distribution of vitiligo disease." (PMID 36359263, 2022). "Given the apparent critical role of IFNγ in driving vitiligo inflammation and its downstream signaling dependent on the JAK1-JAK2 heterodimer, it has also been found that intense and diffuse JAK1 expression is more present within vitiliginous skin compared with healthy tissue." (PMID 34371735, 2021). "Furthermore, the other question which has been puzzling researchers was the initial source of the signature vitiligo cytokine IFNγ." (PMID 33936032, 2021). "In response to IL-12, IL-15, and IL-18, they secrete IFNγ; a signature vitiligo cytokine." (PMID 33936032, 2021). "IFNγ was described as one of the main molecules able to drive the melanocytes toward a senescent phenotype, which is one of the predominant features when analyzing vitiligo-prone melanocytes." (PMID 32974361, 2020). "From a pathophysiology perspective, although the major target cells and antigens are different, MS and vitiligo may have a shared pathologic pathway including increased levels of interferon gamma and IL-17, oxidative stress, and IL2RA gene." (PMID 33082449, 2020). "IFNγ treatment also resulted in the accumulation of reactive oxygen species and the production of proinflammatory cytokines like IL-6 which are considered as important contributing factors facilitating a vitiligo-prone environment in the skin." (PMID 31447854, 2019). "Semi-quantification of their detection has shown significantly higher number of CD56 + Granzyme B+ cells and CD56 + IFNγ+cells in NL compared to L skin of vitiligo patients (n = 6) and a higher number in NL skin of vitiligo patients compared to healthy skin (n = 5)." (PMID 31097717, 2019). "Knowing that NHM upregulate their chemokine production following IFNγ stimulation, we asked whether this chemokine production varies between healthy and vitiligo melanocytes." (PMID 31097717, 2019). "Given the multiple role of IFNγ in vitiligo, inhibition of the Jak-Stat pathway may represent a promising therapeutic strategy." (PMID 31447854, 2019). "Those cells can be an important source of IFNγ production and their presence in repigmented areas could explain the recurrences of vitiligo lesions which often affected the same skin locations." (PMID 31097717, 2019). "Together, these results suggest vitiligo melanocytes are more sensitive to IFNγ stimulation and may have greater chemo-attractive properties." (PMID 31097717, 2019). "Recent data emphasized the key role of the interferon gamma (IFNγ) pathway in vitiligo." (PMID 31097717, 2019).
vitiligo (continued). "Given the apparent critical role for IFNγ in driving vitiligo inflammation and its downstream signaling dependent on the JAK1-JAK2 heterodimer, it is perhaps not surprising that intense and diffuse JAK1 expression is more present within vitiliginous skin compared with healthy tissue." (PMID 31649667, 2019). "We hypothesized that vitiligo is initiated by dysregulation in innate immunity and melanocytes, and that innate immune cells are the initial source of IFNγ production in the skin." (PMID 31097717, 2019). "Similar to the results obtained following H2O2 stimulation, HMGB1- and HSP70-induced IFNγ production by NK and ILCs were dose- and time-dependent and responses from vitiligo melanocytes were significantly higher compared to responses in melanocytes from healthy individuals at the same dose." (PMID 31097717, 2019). "Thus, we reproduced the experiment with NK and total ILCs from PBMC of healthy (C) and vitiligo (V) patients and this time examined their IFNγ responses after stimulation with HMGB1 or HSP70." (PMID 31097717, 2019). "In vitro, direct analysis of skin T-cells from the margins of vitiliginous skin showed that polarized type-1 T cells (CD4+ and particularly CD8+), which predominantly secrete IFNG and TNFA are associated with the destruction of melanocytes during active vitiligo." (PMID 24312346, 2013). "Thus, the pathogenesis of vitiligo may be influenced by the involvement of interferon-gamma and CD8+ T cell-dependent cytokine activity, which is believed to be involved in alopecia areata." (PMID 36475210, 2022). "Thus, while IFNγ clearly plays an important role in vitiligo pathogenesis, it is still unclear whether other IFNs contribute to disease." (PMID 33737930, 2021). "The stress-induced IFNγ production by NK and ILCs from vitiligo subjects were significantly higher compared to healthy subject’s responses at the same dose suggesting vitiligo innate cells were more sensitive to oxidative stress compared to cells from healthy controls." (PMID 31097717, 2019). "In vitiligo affected skin, a significantly higher expression of TNFA, IL6, and IFNG was detected compared with healthy controls and perilesional, non-lesional skin indicating that cytokine imbalance plays an important role in the depigmentation process of vitiligo." (PMID 24312346, 2013). "Recently, through scRNA-seq of vitiligo skin, Xu and colleagues identified a subpopulation of IFN-responsive fibroblasts that secrete IFNγ to recruit and activate CD8 + cytotoxic T cells, which are pivotal in shaping the vitiligo microenvironment." (PMID 40361040, 2025). "The pathogenesis of vitiligo is centrally mediated by cytotoxic CD8+ T cells (CTLs) specific for melanocyte antigens and their production of interferon-gamma (IFN-γ)." (PMID 41327822, 2025). "PRP has been shown to suppress the expression of key proinflammatory cytokines, including interleukin-1 (IL-1), interferon-gamma (IFN-γ), and tumor necrosis factor-alpha (TNF-α), all of which are critically involved in the pathogenesis of vitiligo." (PMID 41226837, 2025). "Interferon-gamma (IFN-γ) drives keratinocyte apoptosis and compromises melanocyte survival, explaining conditions such as vitiligo." (PMID 40271531, 2025). "Highly significant changes in the expression of T cell activation-related genes IFNG, FASLG, GZMA and IL21 and anti-inflammatory genes IL10 and TGFB1 were found in growing feathers of vitiligo-expressing Smyth chickens (P < 0.0001)." (PMID 38720888, 2024). "The present study contributes to confirming a relevant role of the IFNγ/CXCL10 axis and, consequently, of the JAK/STAT pathway in the pathogenesis of vitiligo, highlighting CXCL10 as a possible marker of disease activity." (PMID 37985303, 2024). "A subset of IFNγ-responsive dFBs has been identified to recruit and activate CD8+ cytotoxic T cells during the pathogenesis of vitiligo." (PMID 39213029, 2024).
vitiligo (continued). "They identified a subset of IFNγ-responsive dFBs which are required to recruit and activate CD8+ cytotoxic T cells during the pathogenesis of vitiligo." (PMID 39213029, 2024). "This study sufficiently identified the positive-feedback loop between IFNγ-responsive fibroblasts and CD8+ T cells in vitiligo." (PMID 35950754, 2022). "This study identified that IFNγ-responsive fibroblasts can recruit CD8+ T cells through CXCL9 and CXCL10 in vitiligo." (PMID 35950754, 2022). "CD49a, a marker that distinguishes a subset of CD8+ CD103+ T cells with the cytotoxic potential to produce IFNγ, is expressed in half of epidermal and less than a quarter of dermal CD8+ CD103+ T cells in patients with vitiligo." (PMID 34012438, 2021). "In dogs, we found enrichment of T cell gene signatures, with upregulation of IFNG, TNF, PRF1, IL15, CTSW, CXCL10, and CCL5 in both VKH and vitiligo in dogs compared to healthy controls." (PMID 33384688, 2020). "Several cytokines and chemokines contribute to the development of vitiligo and VKH, including type 1 responses (IFNγ, CXCL9/10/11, IL-12, TNF) type 17 responses (IL-17, CCL20, IL-23) and IL-2, which supports T cell growth and survival." (PMID 33384688, 2020). "To confirm that IFNG and CXCL10, two well-characterized drivers of anti-melanocyte responses, are expressed at the protein level in lesional skin of VKH and vitiligo canines, we performed immunohistochemistry." (PMID 33384688, 2020). "IFNs may have a key role also in vitiligo, as the treatment of different diseases using IFNs may be associated with the onset of vitiligo, notably metastatic melanoma, hepatitis C infections, or during the treatment of skin tumors with imiquimod, an IFN gamma (IFNγ)-releasing agent." (PMID 32974361, 2020). "The vitiligo case exhibited even higher ISG15 and PRF1, while IFNG, TNF, IL12, and IL15 levels were closer to those in healthy controls." (PMID 33384688, 2020). "Stimulation with IFNγ significantly increased both CXCL9 and CXCL10 protein in the supernatant of vitiligo melanocytes, producing on average 4–5 fold more chemokines compared to healthy controls." (PMID 31097717, 2019). "An increase in tumor necrosis factor alpha (TNF-α), interferon-gamma (IFN-γ), and interleukin- (IL-) 1 compared to healthy skin suggests that vitiligo is mediated by cytotoxic T cells and T helper cell-1 (Th1) response." (PMID 28828385, 2017). "Additionally, 3D‐Exos markedly attenuated the expression levels of the activation marker cluster of differentiation 69 (CD69), interferon‐gamma (IFN‐γ), and Granzyme B in CD8+ T cells in both the tail skin and peripheral blood of vitiligo mice." (PMID 38887870, 2024). "Here, we document a sequence of immunologically significant events, including characteristic rises in infiltrating B and αβ T cells as well as evidence of active leukocyte recruitment and cell-mediated immune activities (CCL19, IFNG, GZMA) leading up to visual vitiligo onset." (PMID 38720888, 2024). "However, the levels of IFNG, PRF1, GZMB and CXCR3, CXCL9, CXCL10, CXCL12, and other cytokines also had an upward trend in the vitiligo group." (PMID 37207234, 2023). "Additionally, the researchers revealed that the activated IFNγ-responsive fibroblasts can recruit CXCR3+ T cells and interact with melanocytes by secreting chemokines CXCL9/CXCL10 in vitiligo lesions." (PMID 37809065, 2023). "Activated NK cells (CD56+ / granzyme B+) and IFNγ-producing cells have been identified in the blood and non-lesional skin of patients with vitiligo." (PMID 35643735, 2022). "Thus, the CD8 TRM found in vitiligo and AA are characterized as Tc1-like cells, whereas in the lesional skin of psoriasis, CD8 TRM express IL-17A, IL-22, and IFNγ." (PMID 34884736, 2021). "However, addition of pre-stressed NKs or ILCs from vitiligo patients dramatically increased their own melanocyte production of CXCL9, CXCL10, CXCL11 and IFNγ." (PMID 31097717, 2019).
vitiligo (continued). "Furthermore, inflammatory factors and interleukin (IL) signaling pathway (IL4 and IL10), adaptive immune response (IFNG), and cell apoptosis (FASLG and TNF) also played critical roles in the clarification of the mechanisms of KBL on vitiligo." (PMID 31781265, 2019). "While IFNγ significantly increased the number of CXCR3B + cells in healthy skin, IFNγ had no further effect on vitiligo melanocytes whose CXCR3B expression was already high." (PMID 31097717, 2019). "IFNγ significantly upregulated CXCR3B mRNA expression in both healthy and vitiligo patients." (PMID 31097717, 2019). "Here we demonstrate increased presence of type-1 innate lymphoid cells (NK and ILC1)-producing interferon gamma (IFNγ) in the blood and in non-lesional skin of vitiligo patients." (PMID 31097717, 2019). "We have recently demonstrated increased presence of ILC1 (but not ILC2 or ILC3) in vitiligo blood and skin and these cells to be the initial source of IFNγ, which is involved in early melanocyte apoptosis and subsequent T-cell mediated destruction of melanocytes." (PMID 33936032, 2021). "By comparing these active vitiligo mouse dFBs with the active ACD pAds (dFB_r5), we found that these two cell populations are enriched with highly similar IFNγ-inducible genes, suggesting that the IFNγ-responsive pAds may also contribute to the activation of type 1T cells in the context of ACD." (PMID 39213029, 2024). "This subset of IFNγ-responsive fibroblasts and its pivotal role in the cutaneous EIME of vitiligo lesions have never been elucidated in prior research." (PMID 37809065, 2023).